UBE2MP1 (ubiquitin conjugating enzyme E2 M pseudogene 1)
Gene: Processed pseudogene on chromosome 16 (35,169,692 to 35,170,241, reverse strand). Ensembl gene ENSG00000261461.
Diseases named in the same sentence as UBE2MP1 in open-access papers:
UBE2MP1 is named in the same sentence as 5 diseases in open-access papers, as found by Europe PMC text mining. Sharing a sentence is not in itself a finding about the gene and the disease. The quoted sentences say what the papers report.
cancer (2 papers, 2022 to 2023). A tumor composed of atypical neoplastic, often pleomorphic cells that invade other tissues. "The exploration and analysis of the datasets from the dreamBase databases indicated a universal transcription of UBE2MP1 in either pan-cancers or HCC." (PMID 36214767, 2022).
tumor (1 paper, 2022). "The abrogation of UBE2MP1 not only suppressed tumor cell growth by arresting the cell cycle in the early stages, but also induced cell apoptosis." (PMID 36214767, 2022). "The analysis of the real patients’ clinicopathological features demonstrated that the expression of UBE2MP1 is correlated with severe tumor progress and dismal phenotypes hindering a better prognosis and overall survival." (PMID 36214767, 2022). "The modulation of either miR-145-5p or RGS3 for rescue experiments could significantly recover the phenotypes of tumor cell growth and maintenance induced by UBE2MP1." (PMID 36214767, 2022). "Whereas, the up-regulation of the UBE2MP1 transcript was detected in different tumor tissues." (PMID 36214767, 2022). "Since the parental gene UBE2MP1 is a key mediator of ubiquitination, and has been reported as a tumor-promoter in HCC, we focused on this pseudogene and wondered if the abnormally transcribed UBE2MP1 participates in HCC cell growth dependently or independently to UBE2MP1." (PMID 36214767, 2022). "We concluded and illustrated the tumor-promoting mechanism of UBE2MP1, independent of its parental genes, by modulating the miR-145-5p/RGS3 axis." (PMID 36214767, 2022). "For the real patients’ specimens from our medical center, a high level of UBE2MP1 transcript was detected in HCC tumor samples, and the adjacent non-cancerous liver tissues presented nearly no sign of UBE2MP1 transcription." (PMID 36214767, 2022). "On the other hand, we discovered a specific binding site on the sequence of UBE2MP1 transcript for sponging miR-145-5p, and a remarkable increase of miR-145-5p in HCC cell lines through depleting UBE2MP1 supported the ceRNA effect of UBE2MP1 on defecting miR-145-5p and the tumor-suppressive effect." (PMID 36214767, 2022).
UBE2MP1 also shares sentences with these, for which no sentence is quoted: follicular thyroid adenoma (1 paper); follicular thyroid carcinoma (1); hepatocellular carcinoma (1).